USP36 (ubiquitin specific peptidase 36)
Description:
Deubiquitinase essential for the regulation of nucleolar structure and function. Required for cell and organism viability. Plays an important role in ribosomal RNA processing and protein synthesis, which is mediated, at least in part, through deubiquitination of DHX33, NPM1 and FBL, regulating their protein stability. Functions as a transcriptional repressor by deubiquiting histone H2B at the promoters of genes critical for cellular differentiation, such as CDKN1A, thereby preventing histone H3 'Lys-4' trimethylation (H3K4). Specifically deubiquitinates MYC in the nucleolus, leading to prevent MYC degradation by the proteasome: acts by specifically interacting with isoform 3 of FBXW7 (FBW7gamma) in the nucleolus and counteracting ubiquitination of MYC by the SCF(FBW7) complex. In contrast, it does not interact with isoform 1 of FBXW7 (FBW7alpha) in the nucleoplasm. Interacts to and regulates the actions of E3 ubiquitin-protein ligase NEDD4L over substrates such as NTRK1, KCNQ2 and KCNQ3, affecting their expression an functions. Deubiquitinates SOD2, regulates SOD2 protein stability. Deubiquitinase activity is required to control selective autophagy activation by ubiquitinated proteins. Promotes CEP63 stabilization through 'Lys-48'-linked deubiquitination leading to increased stability. Acts as a SUMO ligase to promote EXOSC10 sumoylation critical for the nucleolar RNA exosome function in rRNA processing. Binds to pre-rRNAs.
Synonyms: KIAA1453; FLJ12851; DUB1
Tractability: Small molecule: a structure with a bound ligand is known. PROTAC: UniProt records ubiquitination sites on it; ubiquitination databases record sites on it; its protein half-life has been measured.
Target class: Enzyme; Hydrolase
Gene: Protein-coding gene on chromosome 17 (78,787,381 to 78,841,441, reverse strand). Ensembl gene ENSG00000055483.
Subcellular location: Nucleus, nucleolus; Cytoplasm
Subcellular location (Human Protein Atlas): Nucleoli; Nucleoli rim; Nuclear speckles
Gene Ontology:
Molecular function: cysteine-type deubiquitinase activity; histone H2B deubiquitinase activity; K48-linked deubiquitinase activity; protein binding; RNA binding
Biological process: chromatin organization; negative regulation of macroautophagy; positive regulation of establishment of protein localization to mitochondrion; protein deubiquitination; regulation of mitophagy; regulation of protein stability; regulation of rRNA processing; nucleolus organization; protein stabilization; regulation of apoptotic process; chromatin remodeling
Cellular component: cytoplasm; nuclear speck; nucleolus
Genetic constraint (gnomAD): Loss-of-function variants: 58 observed, 111.85 expected, observed/expected ratio (o/e) 0.52, 90% interval 0.42 to 0.64. The upper end of that interval is the gene's LOEUF score, 0.64, which puts it in group 2 of 6, group 1 being the genes least tolerant of losing a copy. Missense variants: 1,481 observed, 1,500.7 expected, observed/expected ratio (o/e) 0.99, 90% interval 0.94 to 1.03. Synonymous variants: 627 observed, 596.86 expected, observed/expected ratio (o/e) 1.05, 90% interval 0.98 to 1.12.
Homologues: Orthologues: chimpanzee USP36 (99% identical), macaque USP36 (95% identical), dog USP36 (75% identical), guinea pig USP36 (73% identical), mouse Usp36 (73% identical), rat Usp36 (72% identical), rabbit USP36 (71% identical), pig USP36 (56% identical), zebrafish usp36 (50% identical). Paralogues in human: USP42 (32% identical), USP17L11 (18% identical), USP17L18 (18% identical), USP17L19 (18% identical), USP17L20 (18% identical), USP17L22 (18% identical), USP17L12 (18% identical), USP17L13 (18% identical), USP17L15 (18% identical), USP17L17 (18% identical), USP17L21 (18% identical), USP17L24 (18% identical), and 59 more.
Diseases named in the same sentence as USP36 in open-access papers:
USP36 is named in the same sentence as 37 diseases in open-access papers, as found by Europe PMC text mining. Sharing a sentence is not in itself a finding about the gene and the disease. The quoted sentences say what the papers report.
glioblastoma (7 papers, 2020 to 2025). The most malignant astrocytic tumor (WHO grade IV). "Furthermore, a study observed that high USP36 expression is associated with poor prognosis in patients with glioblastoma." (PMID 38785979, 2024). "More recently, USP36 facilitates the development of glioblastoma through mediating ALKBH5 protein stability." (PMID 38517383, 2024). "There is a direct correlation between elevated USP36 expression and decreased survival in patients diagnosed with glioblastoma." (PMID 38785979, 2024). "USP36 is upregulated in multiple cancers including esophageal carcinoma, glioblastoma, HCC, colorectal cancer, breast cancer, and T cell lymphoma." (PMID 38785979, 2024). "This novel PRL1/USP36/Snail2 axis may be a promising therapeutic target for glioblastoma." (PMID 35111679, 2021). "As a possible ALKBH5 deubiquitination enzyme, Ub‐specific peptidase 36 (USP36) is essential for ALKBH5 stability and AlkBH5‐mediated gene expression regulation in glioblastoma (GBM)." (PMID 40919129, 2025). "Conversely, when USP36 was removed, there was a decrease in ALKBH5 expression, which resulted in the inhibition of tumor growth in glioblastoma xenograft models." (PMID 38785979, 2024). "Aberrant activation of ALKBH5 in glioblastoma (GBM) plays a critical role in tumor growth and progression, and studies have identified a mechanism of regulation of ALKBH5 by USP36." (PMID 39192357, 2024).
ovarian cancer (7 papers, 2015 to 2025). A primary or metastatic malignant neoplasm involving the ovary. "We found that knock-down of USP36 caused hypersensitivity to UV and HU in a human ovarian cancer cell line (OVCAR8)." (PMID 33237263, 2020). "Meanwhile, USP36 expression was negatively associated with the sensitivity of cancer cells to the anti-cancer drug olaparib, as evidenced by analysis of the data from the CellMinerCDB in 43 ovarian cancer cell lines." (PMID 33237263, 2020). "Finally, to establish a causal effect for USP36 in chemosensitivity, we sought to evaluate whether targeting USP36 could sensitize ovarian cancer cells to cisplatin and olaparib." (PMID 33237263, 2020). "While knockdown of USP36 significantly increases the sensitivity of ovarian cancer cells to the DNA replication stress inducer hydroxyurea, while restoring PrimPol expression can reverse this phenomenon." (PMID 40909126, 2025). "It has been shown that USP36 is crucial in ovarian cancer development due to its direct deubiquitylation for PrimPol, of which overexpression correlates with poor prognosis." (PMID 38517383, 2024). "USP36 has recently attracted increasing attention in cancer studies from ovarian cancer to breast cancer, lung cancer, hepatocellular carcinoma, esophageal squamous carcinoma, and glioblastoma." (PMID 38876304, 2024). "In future work, it will be important to screen and identify USP36 specific inhibitors that suppress USP36 activity in cancer cells and that will consequently inhibit PrimPol-dependent repriming and sensitize ovarian cancer to therapeutic drugs." (PMID 33237263, 2020). "A positive correlation between USP36 and PrimPol protein levels (P = 0.0286, Pearson r = 0.7205) was observed in ovarian cancer cell lines." (PMID 33237263, 2020). "The Kaplan–Meier Plotter tool was used to evaluate the correlation of USP36 expression with clinical outcome in ovarian cancer patients." (PMID 33237263, 2020). "As a proof of concept for targeting this pathway, we show that depletion of USP36 sensitizes ovarian cancer cells to therapeutic response by inhibiting PrimPol-mediated fork restart." (PMID 33237263, 2020). "We then performed immunohistochemical staining of USP36 and PrimPol in an ovarian cancer tissue microarray containing a cohort of ovarian cancer samples (n = 140)." (PMID 33237263, 2020). "Another study that set out to identify both up- and down-regulated genes in ovarian cancer for use in diagnosis determined that USP36 was overexpressed." (PMID 25605410, 2015). "Indeed, we also demonstrate upregulated USP36 in ovarian cancer patients that correlates with higher PrimPol level and poor prognosis." (PMID 33237263, 2020). "To test our hypothesis, we examined the correlation between the expression of USP36 and PrimPol proteins in human ovarian cancer cells and specimens." (PMID 33237263, 2020). "In addition, given PrimPol-mediated adaptive response to multiple drugs, such as cisplatin, we evaluated whether USP36 plays a role in response to therapy in ovarian cancer cells." (PMID 33237263, 2020). "In ovarian cancer tissues, USP36 overexpression is observed to positively correlate with the level of PrimPol expression and poor prognosis, indicating that the USP36-PrimPol axis may play an important regulatory mechanism in the cancer pathogenesis and treatment." (PMID 33237263, 2020). "Therefore, targeted inhibition of USP36 to block PrimPol-mediated replication fork restart, combined with the use of DNA replication stress pathway inhibitors, may enhance the chemosensitivity of ovarian cancer cells, providing a novel approach for ovarian cancer treatment." (PMID 40909126, 2025). "USP36, a USP member, was initially isolated as a DUB enzyme from ovarian cancer cells." (PMID 38876304, 2024). "More importantly, USP36 was identified in sera of 36% of cases from ovarian cancer patients compared with none from healthy subjects." (PMID 25605410, 2015).
breast carcinoma (6 papers, 2021 to 2024). "Our analysis revealed that high USP36 levels were linked to shorter survival rates in ERα positive breast cancer patients." (PMID 39215346, 2024). "Mechanistically, we identified USP36 promoted breast cancer development by decreasing K48-linked ubiquitinating of ERα protein, thereby enhancing ERα signaling activity and tamoxifen resistance." (PMID 39215346, 2024). "What’s more, we also revealed elevated levels of USP36 are associated with reduced survival rates in breast cancer patients undergoing tamoxifen therapy." (PMID 39215346, 2024). "Multiple studies have confirmed the high expression of USP36 in breast cancer tumor tissues and its association with poor patient prognosis." (PMID 38785979, 2024). "Several studies have reported high USP36 expression in breast cancer tissues, which is strongly associated with a poor prognosis in patients." (PMID 38785979, 2024). "Furthermore, in this study we indicated that USP36 facilitate breast cancer development via adjusting K48-linked deubiquitinating of ERα protein, and then enhancing ERα signaling activity." (PMID 39215346, 2024). "In our study, we found that USP36 interacts with ERα, leading to the suppression of ERα polyubiquitination and degradation in breast cancer cells, which indicated that USP36 linked to breast cancer proliferation and invasion via estrogen signaling." (PMID 39215346, 2024). "We further examined the localization of USP36 and ERα in breast cancer cells using an immuno-staining assay." (PMID 39215346, 2024). "Additional immunohistochemistry analysis of 65 breast cancer samples demonstrated a positive correlation between USP36 and ERα." (PMID 39215346, 2024). "Using this model, we assessed how USP36 influences the breast cancer phenotype and ERα signaling in an endocrine-resistant context." (PMID 39215346, 2024). "The CCK8 assay indicated USP36 instead of its catalytically inactive mutant (C131A) overexpression significantly promoted ER positive breast cancer cell proliferation." (PMID 39215346, 2024). "We further examined the expression of USP36 in human breast cancer and found that both the mRNA and protein level of USP36 were increased in breast malignancies based on data from the TCGA database." (PMID 39215346, 2024). "It is interesting to note that our results suggest USP36 as a novel biomarker for treatment of breast cancer." (PMID 39215346, 2024). "The CCK8 assay showed that depleting USP36 restored tamoxifen’s inhibitory effect in breast cancer cells." (PMID 39215346, 2024). "USP22 and USP36 regulate the cellular turnover of c-MYC in breast cancer, and c-MYC expression is stabilized by USP28 and USP37 in colon carcinoma and lung cancer, respectively." (PMID 39664521, 2024). "It was reported that USP22 and USP36 promote breast cancer growth targeting the oncogenic protein, c-Myc." (PMID 34575114, 2021). "Similarly, the results obtained from the transwell and wound healing assays suggested that the migratory capacity of breast cancer cells was notably hampered after USP36 deprivation." (PMID 39215346, 2024). "Based on these results, we suggest that USP36 may serve as a potential enhancer of ER signaling in breast cancer." (PMID 39215346, 2024). "Furthermore, the CCK8 assay indicated that USP36 depletion resulted in the inhibition of breast cancer cell proliferation, a phenotype that was partially rescued upon further ERα overexpression." (PMID 39215346, 2024). "We also assessed the protein level of USP36 in breast cancer patient samples using immunohistochemistry (IHC), interestingly, Breast cancers also showed significant increases in USP36 expression (11/55 vs 43/65; P < 0.001) which was consistent with the result from TCGA database." (PMID 39215346, 2024). "USP36 depletion was confirmed using real-time PCR and Immunoblot analysis, and significantly impaired the proliferation of ER-positive breast cancer cells, as indicated by the CCK8 assay." (PMID 39215346, 2024).
breast carcinoma (continued). "A novel modulator of estrogen signaling modulation of USP36 activity or gene expression level may be an attractive treatment option for breast cancer." (PMID 39215346, 2024). "Overall, USP36 significantly contributes to the advancement of ERα positive breast cancer." (PMID 39215346, 2024). "In order to further examined the impact of USP36 on the ER positive breast cancer phenotype, by overexpressing of USP36 wild-type (WT) plasmid, and USP36 catalytically inactive mutant (C131A), We found that USP36 WT and USP36 C131A was successfully achieved, as validated by western blotting." (PMID 39215346, 2024). "In addition, GSEA indicated that the HALLMARK_ESTROGEN RESPONSE gene set signature was significantly enrichment in the presence of USP36 high expression based on the expression in breast cancer tissue from TCGA database (NES = 2.01; P < 0.05)." (PMID 39215346, 2024). "Our study revealed the possibility that inhibiting USP36 combined with tamoxifen could provide a potential therapy for breast cancer." (PMID 39215346, 2024). "Furthermore, both the mRNA and protein levels of USP36 was also elevated in breast cancer samples that were positive for ERα." (PMID 39215346, 2024). "To inquire whether ERα is contained in USP36-mediated proliferation, migration and apoptosis properties of breast cancer, we carried out several rescue experiments." (PMID 39215346, 2024). "In conclusion, our results demonstrate that USP36 modifies the ubiquitination of estrogen receptors and tamoxifen resistance, which may provide a new therapeutic target for the treatment of breast cancer." (PMID 39215346, 2024). "In different cancers, cellular turnover of c-MYC has been regulated by different USPs, with notable examples including the maintenance of c-MYC turnover by direct physical interactions of USP28 in colon carcinoma, USP36 in breast carcinoma and USP37 in lung cancer." (PMID 36985413, 2023). "Among them, USP28 binds to Myc through an interaction with nucleoplasmic FBW7α, which is essential in breast and colon tumor cell proliferation, and USP36 binds to nucleolar Fbw7γ and controls the nucleolar degradation pathway of c-Myc in lung and breast cancer cells." (PMID 37190313, 2023). "USP36 increases breast cancer cell proliferation by deubiquitinating c-Myc in the nucleolus and inhibiting c-Myc proteasomal degradation mediated by SCFFbw7, reciprocally, Myc targets USP36 for promoting its transcription." (PMID 34575114, 2021). "Furthermore, in the model of endocrine resistant breast cancer cells, inhibiting USP36 could recover tamoxifen sensitivity in vivo and in vitro." (PMID 39215346, 2024). "In this study, we identify Ubiquitin-specific peptidase 36 (USP36) as a key deubiquitinase involved in ERα signaling and the advancement of breast cancer by deubiquitinases siRNA library screening." (PMID 39215346, 2024). "USP36 can also regulate the ubiquitination level of PKM2, thereby increasing its protein expression, and promote glycolysis of breast cancer cells through the “Warburg effect”." (PMID 37190313, 2023). "For instance, in breast carcinoma USP22 and USP36 are known to regulate the cellular turnover of c-MYC." (PMID 36985413, 2023). "In vitro and in vivo studies showed that USP36, but not its catalytically inactive mutant (C131A), could promote breast cancer progression through ERα signaling." (PMID 39215346, 2024). "Interestingly, the survival data indicated a negative correlation between high USP36 expression and survival outcomes in breast cancer patients undergoing tamoxifen therapy." (PMID 39215346, 2024).